SERPINC1 (serpin family C member 1)
Diseases named in the same sentence as SERPINC1 in open-access papers (continued):
Sharing a sentence is not in itself a finding about the gene and the disease.
Alcohol (2 papers, 2020 to 2025). "For instance, we were able to link S100A11 and SERPINC1, proteins associated with pQTLs in hotspots 17 and 18, to alcohol dependence through their distant pQTL variants located in ADH1C." (PMID 32778093, 2020). "Our results suggest that S100A11 and SERPINC1 may be involved in molecular mechanisms underlying the association between rs698 and alcohol dependence." (PMID 32778093, 2020). "The study implies that inflammation associated with the development of alcohol dependence might be partially mediated by S100A11 and SERPINC1 proteins." (PMID 32778093, 2020).
Alzheimer disease (2 papers, 2021 to 2024). A progressive, neurodegenerative disease characterized by loss of function and death of nerve cells in several areas of the brain leading to loss of cognitive function such as memory and language. "We also found distinct variants (high PP.H3) in KAT8 with FVC for Alzheimer’s disease (from GWAS meta-analysis), in PTCH1 with FVC and FEV1/FVC for fluid intelligence and reaction time and in SERPINC1 with FVC for reaction time." (PMID 39544701, 2024).
bleeding disorders (2 papers, 2017 to 2022). "It downregulates antithrombin III (AT) protein production by targeting the SERPINC1 gene in the treatment of patients suffering from haemophilia and rare bleeding disorders (RBDs)." (PMID 35352626, 2022).
colon cancer (2 papers, 2009 to 2024). "Subsequently, we explored the association of SERPINC1 with multiple clinicopathologic features in patients with colon cancer by analysing our own cohort of 212 patients with colon cancer." (PMID 38923313, 2024). "In conclusion, we found that SERPINC1 may be closely associated with liver metastasis of colon cancer." (PMID 38923313, 2024). "To verify that SERPINC1 is indeed associated with liver metastasis of colon cancer, first, we examined SERPINC1 expression in liver metastasis tissues of colon cancer and in situ colon cancer tissues using immunohistochemical staining in 15 colon cancer patients with synchronous liver metastasis." (PMID 38923313, 2024). "Subsequently, we found that high expression of SERPINC1 was associated with poorer T stage, N stage and deeper vascular invasion in colon cancer patients, these results suggest that SERPINC1 may be an important molecular marker for predicting the prognosis of colon cancer patients." (PMID 38923313, 2024). "The high expression of SERPINC1 may also be associated with oxaliplatin resistance in colon cancer." (PMID 38923313, 2024). "Relationship between the expression of SERPINC1 protein and clinicopathological parameters in colon cancer." (PMID 38923313, 2024). "Immunohistochemical staining also showed greater expression of SERPINC1 in liver metastases from colon cancer than in normal colon tissues and in situ colon cancer tissues." (PMID 38923313, 2024). "We first used the Timer web site analysis to conclude that SERPINC1 affects the infiltration of multiple immune cells in colon cancer." (PMID 38923313, 2024). "By analysing the liver metastasis samples of colon cancer in Geo Database, we found that the expression of SERPINC1 in liver metastasis samples was higher than that in colon cancer tissues in situ." (PMID 38923313, 2024). "In the Van Allen cohort 2015 pairs, we found that high expression of SERPINC1 renders colon cancer patients resistant to treatment with anti‐CTLA‐4." (PMID 38923313, 2024). "Clinical data obtained from our hospital were used to explore the impact of SERPINC1 on the prognosis of colon cancer patients." (PMID 38923313, 2024). "The results showed that the expression of SERPINC1 was significantly increased in liver metastases from colon cancer." (PMID 38923313, 2024). "We first analysed on the K–M website that high expression of SERPINC1 contributes to lower 5‐year survival in patients with colon cancer." (PMID 38923313, 2024). "The K–M survival curve showed that SERPINC1 was negatively correlated with the survival probability of colon cancer patients." (PMID 38923313, 2024). "In the results, we first noted that high expression of SERPINC1 was associated with higher CEA and CA19‐9 levels in circulating blood of colon cancer patients." (PMID 38923313, 2024). "To explore the mechanisms by which Serpinc1 influences various biological behaviours of colon cancer cells, we performed enrichment analysis of its function and pathway using single‐cell and transcriptome data." (PMID 38923313, 2024). "Bioinformatics predicted that SERPINC1 affects metastasis of colon cancer through epithelial‐mesenchymal transition (EMT)." (PMID 38923313, 2024). "Using TGF‐β treated colon cancer cells as a control, we found that knockdown of SERPINC1 inhibited the enhanced migratory ability of colon cancer after TGF‐B treatment." (PMID 38923313, 2024). "Subsequently, using the CCK‐8 experiment, we found that knockdown of SERPINC1 significantly reduced the proliferation ability of colon cancer cells." (PMID 38923313, 2024). "Furthermore, this cohort also suggested that colon cancer patients with high expression of SERPINC1 had a lower 5‐year survival after treatment with Ctla‐4." (PMID 38923313, 2024). "In this study, we confirmed that the knockdown of SERPINC1 could significantly inhibit the proliferation and migration of colon cancer cells in vitro." (PMID 38923313, 2024).
colon cancer (continued). "Finally, the effect of SERPINC1 on the sensitivity of colon cancer patients to immune checkpoint therapy was evaluated." (PMID 38923313, 2024). "The results showed that the expression of SERPINC1 in colon cancer tissues was significantly higher than that in normal colon tissues, and SERPINC1 was significantly higher in metastatic colon cancer tissues than in non‐metastatic colon cancer tissues." (PMID 38923313, 2024). "The results showed that SERPINC1 was closely related to the EMT behaviour in colon cancer." (PMID 38923313, 2024). "In addition, when analysing CellMiner data, we also found that high expression of SERPINC1 can contribute to resistance to multiple drug therapies in colon cancer patients, such as oxaliplatin, fenvelamine and nelarabine." (PMID 38923313, 2024). "We first used transwell experiments and found that TGF‐β could significantly promote the migration of colon cancer cells, but this increase in migration capacity could be reversed by knockdown of SERPINC1." (PMID 38923313, 2024). "Finally, clonogenic experiments showed that knockdown of SERPINC1 significantly reduced the monoclonal ability of colon cancer cells." (PMID 38923313, 2024). "Clinical development of novel SERPINC1‐targeted molecular drugs may be helpful in the prevention and treatment of liver metastases from colon cancer." (PMID 38923313, 2024). "Our analysis of multiple drug sensitivity databases found that high expression of SERPINC1 may contribute to resistance to anti‐CTLA‐4 therapy in patients with colon cancer." (PMID 38923313, 2024). "This suggests that the increased expression of SERPINC1 may be related to the pathogenesis of colon cancer." (PMID 38923313, 2024). "This process may depend on SERPINC1 to promote the EMT behaviour of colon cancer cells." (PMID 38923313, 2024). "Knockdown of SERPINC1 in colon cancer cells inhibited TGFβ‐induced high expression of VIM, while knockdown of SERPINC1 in colon cancer cells restored TGFβ‐induced reduction of Cdh1 expression." (PMID 38923313, 2024). "The results of immunohistochemical staining also indicated that the expression of SERPINC1 was significantly higher in colon cancer tissues than in normal colon tissues." (PMID 38923313, 2024). "Furthermore, western blot experiments also showed that SERPINC1 regulates the migratory capacity of colon cancer cells by regulating the expression of VIM and Cdh1 in colon cancer cells." (PMID 38923313, 2024).
haemophilia (2 papers, 2017 to 2022). "Disruption of the Serpinc1 gene by a single AAV vector system restored hemostasis in hemophilia B mice." (PMID 28646206, 2017). "To correct the bleeding tendency of haemophilia using a single AAV vector system, we examined whether disruption of the AT gene (Serpinc1) by CRISPR/Cas9 could be used for haemophilia." (PMID 28646206, 2017).
heart failure (2 papers, 2017 to 2021). Inability of the heart to pump blood at an adequate rate to meet tissue metabolic requirements. "Numerous studies proved that reduced SERPINC1 have a superiority in predicting many disorders (e.g. heart failure, kidney diseases)." (PMID 29285290, 2017).
hemophilia A (2 papers, 2022 to 2024). The most common form of hemophilia characterized by spontaneous or prolonged hemorrhages due to factor VIII deficiency. "Furthermore, a very similar hybrid strategy was developed to disrupt Serpinc1 while knocking in human F8 in the mouse model for hemophilia A." (PMID 38785523, 2024). "Hemophilia A and B are caused by a defective activation of Factor VIII and IV, respectively, leading to improper activation of thrombin by antithrombin encoded by the SERPINC1 gene." (PMID 36286056, 2022). "Thus, the degradation of this gene is expected to treat both hemophilia A and B. In a murine model, the inactivation of Serpinc1 gene by LNP-encapsulated siRNA has been examined with a therapeutic outcome." (PMID 36286056, 2022).
HIV-1 infection (2 papers, 2011 to 2022). The type species of lentivirus and the etiologic agent of acquired immunodeficiency syndrome (AIDS). "Our in vitro results suggest that treatment with high doses of estrogen and progesterone promotes the expression of host antiviral factors Secretory leukocyte protease inhibitor (SLPI) and Serpin family C member 1 (SERPIN C1), among others produced in response to HIV-1 infection." (PMID 35062299, 2022).
psoriasis (2 papers, 2022 to 2025). An autoimmune condition characterized by red, well-delineated plaques with silvery scales that are usually on the extensor surfaces and scalp. "A few DEPs, such as SERPINC1, SERPINF2, F2, PLXDC2, and TYMP, were also involved in regulating blood coagulation and angiogenesis, which plays an essential role in the pathogenesis and maintenance of psoriasis." (PMID 36483564, 2022).
Atrophy (1 paper, 2020). Any weakening or degeneration, especially through lack of use. "Positive selection was detected in two genes involved in antithrombin (SERPINC1) and muscle atrophy (AARS)." (PMID 32184370, 2020).
breast invasive carcinoma (1 paper, 2024). "Amplification was found to be the most prevalent alteration type for SERPINC1 and PLAT, with high amplification frequencies notably observed in UCS, liver hepatocellular carcinoma (LIHC), CHOL, and breast invasive carcinoma (BRCA)." (PMID 39179711, 2024).
cholangiocarcinoma (1 paper, 2024). A carcinoma that arises from the intrahepatic biliary tree (intrahepatic cholangiocarcinoma) or from the junction, or adjacent to the junction, of the right and left hepatic ducts (hilar cholangiocarcinoma). "Our radar plots revealed that F3, SERPINC1, F2, PLG, and PLAT exhibited the highest positive correlation with TMB in uterine carcinosarcoma (UCS), cholangiocarcinoma (CHOL), CHOL, thymoma (THYM) and LGG, respectively." (PMID 39179711, 2024).
chronic pancreatitis (1 paper, 2021). A chronic inflammatory process causing damage and fibrosis of the pancreatic parenchyma. "Higher serum levels of SERPINC1 with sialylation and fucosylation in PC patients as compared to normal or chronic pancreatitis subjects has been reported." (PMID 34199928, 2021).
diabetic retinopathy (1 paper, 2021). "Proteomics analysis has identified multiple proteins in the serpin family including both Serpinc1 and Serpinf2 as potential serum biomarkers of retinal inflammation in diabetic retinopathy." (PMID 34440888, 2021).
myopia (1 paper, 2023). "Antithrombin-III (SERPINC1), fibrinogen gamma chain (FGG), and fibrinogen beta chain (FGB) are potential novel biomarkers for myopia." (PMID 36674802, 2023).
retinal vein occlusion (1 paper, 2020). An occlusion of the retinal vein. "SERPINC1 or Antithrombin III deficiency has been associated with retinal vein occlusion, consistent with its role as an anti-clotting agent." (PMID 33217969, 2020).
cancer (36 papers, 2007 to 2026). A tumor composed of atypical neoplastic, often pleomorphic cells that invade other tissues. "Among them, five targets (APOH, CD14, ICAM1, LRG1 and SERPINC1) were reported to be associated with other cancers or prognostic significance." (PMID 34199928, 2021). "We used transcriptomic data and immunohistochemical staining to explore the expression of SERPINC1 in normal, cancer, and liver metastases tissue from CRC patients." (PMID 38923313, 2024). "Our analysis identified that C1S, F3, and PLAT as genes with notably high expression, while PLG, SERPINC1, and F2 exhibited lower expression levels across most cancers." (PMID 39179711, 2024). "The association between Serpinc1 and the Pi3K/AKT pathway and how the Serpinc1 protein exerts its effects on cancer cells require further investigation." (PMID 35992834, 2022). "SERPINC1 inhibits thrombin-induced tumor growth and angiogenesis, impairing proliferation and migration of cancer cells." (PMID 34907282, 2021). "SERPINC1 has been shown to regulate the biological behaviour of a variety of malignancies." (PMID 38923313, 2024). "SERPINC1 is recognized as a key gene in the processes of cancer cell proliferation and migration." (PMID 38203636, 2023). "In conclusion, this study provides a strong support for the synergistic effect of nab-PTX combined with anti-PD-1 antibody in inhibiting tumor growth, enhancing immune responses, and suppressing Serpinc1 gene expression and emphasizes the role of Serpinc1 overexpression in cancer development." (PMID 35992834, 2022). "We sought to functionally validate the role of Serpinc1 in cancer progression with LLC cells." (PMID 35992834, 2022). "Actually, we observed that Serpinc1 overexpression activated the phosphorylation levels of Pi3K/AKT, thereby illustrating that the possible mechanism of the Serpinc1 gene involved in cancer progression may be due to signal transduction of the Pi3K/AKT pathway." (PMID 35992834, 2022). "Gene Hsa.462 (official symbol SERPINC1) has been shown to be related to cancer cell proliferation." (PMID 17316436, 2007). "In addition, in some cancers, SERPINC1 promotes tumour migration, invasion, and angiogenesis." (PMID 38923313, 2024). "Serpinc1 could inhibit tumor migration, invasion, and angiogenesis in certain cancers." (PMID 34881176, 2021). "In the majority of cancer types, F3, PLAT, and C1S exhibited significantly stronger positive correlations with stromal, immune and ESTIMATE scores compared to F2, PLG, and SERPINC1." (PMID 39179711, 2024). "Western blotting data analysis confirmed the upregulation of CLU, ITIH4, SERPINC1, and C1RL in endometrial and exosome cancer sera compared to those of control subjects." (PMID 34298850, 2021). "Notably, relatively lower methylation levels for SERPINC1 and PLAT were observed in most cancers than that in normal groups." (PMID 39179711, 2024). "In addition, SERPINC1, APOA4, APOE and ITIH4 are described deviated in the serum of hyperplasia or cancer patients by two teams." (PMID 37091170, 2023). "Combined with the survival analysis results, we speculated that SERPINC1 and PKM play important roles, namely, cancer-suppressing and cancer-promoting functions, respectively, under hypoxia exposure." (PMID 33690171, 2021). "However, no research has shown that KNG1, FBN1, MATN3, and SERPINC1 play an important role in cancer chemotherapy resistance." (PMID 34737677, 2021).
tumor (26 papers, 2011 to 2025). "It has been reported that the high expression of SERPINC1 is associated with the malignant growth of many tumours." (PMID 38923313, 2024). "We detected the significant downregulation of the expression of genes encoding acute phase proteins (e.g., FBG, FGA, and FGG) and tumor-associated genes such as SERPINC1 and F2." (PMID 38203636, 2023). "Nearly all of the identified protein-coding genes exhibited significant differential expression between tumor and normal tissues, with the notable exception of SERPINC1." (PMID 40564071, 2025). "Through the functional enrichment analysis, we determined several critical tumor-related functions of the Serpinc1 gene, such as cell adhesion, proliferation, and response to wound healing, worthy of being further investigated." (PMID 35992834, 2022). "Serpinc1 is a serine protease inhibitor in the coagulation cascade, but its role in tumor biology remains obscure." (PMID 34881176, 2021). "SERPINC1 encodes antithrombin III (ATIII), a serine protease inhibitor whose specific role in tumor biology is not yet clear." (PMID 39179711, 2024). "Meanwhile, SERPINC1 is known to induce apoptosis in HCC cells, inhibit M2 macrophage polarization, and act as a tumor suppressor." (PMID 41228357, 2025). "In contrast, SERPINC1 showed no significant differential expression, indicating that its expression levels remained relatively stable between tumor and normal samples." (PMID 40564071, 2025). "Further, we examined the promoter methylation levels of DELMRGs and found that several genes (such as OAS2, KALRN, SLC16A7, PER2) had significantly lower methylation levels in tumor samples, while several genes (SLC6A3, CDO1, and SERPINC1) were significantly higher methylated." (PMID 37795453, 2023). "The expressions of APOB, FGA, FGG, APOA1, and F2 were significantly down-regulated in the TCGA-LIHC cohort (P<0.05), but SERPINC1 levels were not significantly different between normal and tumor tissues (P>0.05)." (PMID 33834191, 2021).
infection (20 papers, 2009 to 2026). The state of being infected such as from the introduction of a foreign agent such as serum, vaccine, antigenic substance or organism. "HBEC ALI cultures were pretreated apically with individual recombinant SERPINA1, SERPINE1, and SERPINC1 proteins, and the infection was monitored over time." (PMID 35532162, 2022). "The transcriptome data show over-expression of complement component 1 (C1S), an anti-thrombin peptide (SERPINC1), and fibrinogen beta chain (FGB) during virulent infection." (PMID 19216742, 2009). "To confirm whether the “detrimental” proteins enhanced SARS-CoV-2 infection, we conducted in vitro VeroE6 infection assays using purified recombinant VIM, SERPINC1, and S100A9 across the range of concentrations detected in the saliva." (PMID 38007005, 2024).
cardiovascular disease (5 papers, 2021 to 2023). "SERPINC1 was also highly represented in cardiovascular diseases and by GO enrichment, but its potential as biomarker in HF has not been described up to now." (PMID 36915695, 2023). "More importantly, both ratios of VWF:Plasminogen and SerpinC1:Plasminogen were associated with reverse LV remodeling in post-AMI patients, independent of other cardiovascular disease risk factors." (PMID 36613770, 2022).
kidney diseases (5 papers, 2013 to 2024). "Notably, among these abnormally expressed proteins, 19 proteins were reported as kidney disease markers (Ada, Ambp, Anxa1, B2m, Camp, Col1a1, Cp, Ggt1, Glb1, Lgfbp7, Lifr, Lpl, Plau, Ptgds, S100a8, Serpinc1, Serpina3k, Tff1, and Vtn) (highlight in green)." (PMID 31708494, 2019).
autosomal dominant disease (3 papers, 2016 to 2024). Autosomal dominant form of disease. "As AT deficiency is an autosomal dominant hereditary disorder, the most common genetic mutations causing type I AT deficiency are missense/nonsense point mutations, as well as small deletions/insertions which cause frameshifts within SERPINC1 and thus prevent the expression of AT." (PMID 27708219, 2016).